CD24 (CD24 molecule)
Diseases named in the same sentence as CD24 in open-access papers (continued):
Sharing a sentence is not in itself a finding about the gene and the disease.
tumor (continued). "The Id1+/GFP+ cells in the Id1C3-Tag model are predominantly of the CD29+/CD24+ phenotype, with a 1.6-fold higher proportion of cells expressing both CD29 and CD24 compared to the Id1−/GFP− cells which comprise the bulk of the tumor." (PMID 32766238, 2020). "The results showed that, compared with the control group, CD24, CD44, N-Cadherin, β-catenin, and Vimentin in tumor tissues before NAC were significantly overexpressed, and CD24, CD44, E-cadherin, N-cadherin, β-catenin, and Vimentin were significantly lower expressed in paracancer tissues before NAC." (PMID 33282946, 2020). "Dormant tumor cells from the liver were recovered only from the FAC/AIT group 2–3 months after culture ex vivo (FAC/AIT L) and showed similar characteristics as MMC for the expression of neu, EpCAM, or predominant CD24+CD44+ fraction." (PMID 33115528, 2020). "In contrast, the immortalized nontumorigenic cell line ARPE‐19, which is incapable of tumor formation in vivo, exhibited extremely low CD24 expression." (PMID 32394616, 2020). "Simultaneously, CD24 expression influences type II and III tumor recurrence." (PMID 32466488, 2020). "In addition, therapeutic blockade of the CD24 and SIGLEC10 interaction and the MHC class I molecules and LILRB1 interaction accompanied with enhanced TAM phagocytosis towards tumor cells." (PMID 33224886, 2020). "Moreover, immunohistochemistry was conducted to analyze CSCs markers (CD44 and CD24) and EMT markers (E-cadherin, β-catenin, vimentin, and N-cadherin) in benign breast lesions (control), paracancer tissues, and tumor tissues." (PMID 33282946, 2020). "Therefore, in this study, we loaded CD24 with DC–CIKs and explored the efficacy and safety of DC/CIK-CD24 cells’ reinfusion in HCC patients after radical resection of the tumor." (PMID 33324558, 2020). "In contrast, CD24+/CD15- cells failed to initiate tumour formation following 10 transplantations (p = 0.012)." (PMID 30657775, 2019). "Interestingly, rare tumours did arise from the CD15+/CD24- and CD15-/CD24- populations indicating that within the CD24- population resides a TIC that cannot be selected for by CD15." (PMID 30657775, 2019). "Considerable evidence indicates that cell membrane-localized CD24 immunostaining was observed in well-differentiated sites with pearl formation, whereas cytoplasm-localized CD24 immunostaining was observed at tumor invasion sites without keratinized cells." (PMID 31614769, 2019). "Immunohistochemistry study revealed that tumour specimens from both oral cavity and peritoneum were negative for tumour necrosis factor alpha and CD24 but positive for CD44 and CD36." (PMID 31645882, 2019). "The main advantage of this system was that it allowed us to experiment with different administration schemes and monitor the effects on the entire tumor cell population, as reflected in the number of tumorspheres, and on the CSC subpopulation (CD44+CD24-/low), as analyzed by FACS, at the same time." (PMID 31627418, 2019). "In this study, we present a new third-generation CAR against CD24, a promising antigen overexpressed in multiple tumors with high prevalence on CSCs, and analyzed its functionality in CAR-NK cells in OC cell lines and patient-derived primary tumor samples." (PMID 30717444, 2019). "It has been reported that the surface markers such as CD133, in combination with CD29/CD24 and CD44/CD166, may correlate with high Wnt activity and identify stem cells in various tumour types and their possible interaction with the microenvironment." (PMID 31511776, 2019). "In addition, treating TNBC cells with IFNβ suppresses the CSC properties, resulting in decreased tumor sphere formation, EMT expression, and migration, thereby promoting an epithelial phenotype with reexpression of CD24." (PMID 31505803, 2019). "Our results demonstrated that overexpression of miR‐200c resulted in an obvious decrease in the number and diameter of tumour spheres formed from sorted CD44+CD24− phenotype SKBR3‐S but not MCF‐7‐S cells." (PMID 31599500, 2019).
tumor (continued). "IHC/immunofluorescence analysis of CD24+ and CD24- cell-initiating tumours identified diffuse CD24 expression throughout both tumour populations that did not co-label with GFAP or Olig2+." (PMID 30657775, 2019). "CSCs have been identified and isolated, based on the expression of specific molecules, such as CD24, CD34, CD44, CD133, and aldehyde dehydrogenase (ALDH), and are able to regenerate tumor mass from a small number of cells when implanted into immunodeficient mice." (PMID 31013960, 2019). "Therefore, we can further assume that after tumor cell invasion, DAXX reduces intracellular CD24 expression in the nucleus." (PMID 31614769, 2019). "In addition, CD24 was overexpressed in aggressive HCC cell lines and the tumor tissues of patients with recurrent HCC based on the expression of EGR, an early growth response protein." (PMID 31614769, 2019). "Tumor-initiating cells (TICs), also known as cancer stem cells (CSCs), are a small subpopulation of cells in the tumor which can be recognized by several cell surface markers, such as CD133, CD24, CD44, and Bmi-1." (PMID 30081498, 2018). "Taking advantage of the tumors predominantly composed of CD24+CD29high cells, we transplanted 6 × 104 FACS-sorted Lin− cells (depleted of hematopoietic and endothelial cells) from a p18−/−;Brca1MGKO tumor and a p16−/−;Brca1MGKO tumor into eight MFPs of NSG mice (four for each cell type)." (PMID 29996906, 2018). "In hepatocellular carcinoma derived-xenografts, using a humanized monoclonal anti-CD24 antibody had anti-tumor effects, while there was no data on the eradication of the pool of cancer stem cells." (PMID 30551640, 2018). "Emergence of CD44+/CD24+ MCF7 cells, also positive for another stem cell marker CD49f, could result from increased stemcell-like populations in the hypoxic tumor microenvironment in vivo." (PMID 29510720, 2018). "Phenotyping these tumor cells identified a subpopulation of CD29+ and E-cadherin-expressing (CD29+E-cad+) cells enriched for cell surface antigenic markers of primitive cell phenotypes, namely CD24 and CD133 (CD24highCD133+E-cad+)." (PMID 30029671, 2018). "To answer this question, we performed unbiased comparative transcriptomic and functional gene enrichment analyses between MPS vMCF-7∆Raf1 1GX-M (that show CD24−/low) and highly invasive CD24−/low basal-like cells isolated from matching vMCF-7∆Raf1 tumor xenografts as previously demonstrated." (PMID 30180881, 2018). "To determine whether CD24 marks sorafenib-resistant HCC cells, we examined its expression by qRT-PCR in the tumor and the corresponding adjacent tissues of HCC patients (n = 70)." (PMID 29844385, 2018). "The ex vivo EGFP+ or hypoxic population contains an average of 8% CD24+ cells, whereas the non-hypoxic or EGFP− population contains much higher numbers of CD24+ cells at approximately 13%, suggesting that the hypoxic TME favors tumor cells with the CD24−/low CSC-like characteristics." (PMID 29510720, 2018). "Although the EGFP+ tumor cells displayed robust mTOR phosphorylation, the mTOR inhibitor, rapamycin, did not strongly affect the CSC-associated CD24 and CD44 markers (data not shown)." (PMID 29510720, 2018). "We therefore analyzed Cd24 expression on liver cells, and found Cd24 was expressed on hematopoietic cells, but not hepatocytes or tumor cells of HCC and naive mice." (PMID 29423273, 2018). "This might be because that SK-BR-3 had lower CD44/CD24 ratio compared to MDA-MB-231, which might also contribute to slower tumor migration and metastasis." (PMID 29062075, 2017). "Conversely, pharmacologic targeting of Aurora-A restores chemosensitivity through inhibition of SMAD5 transcriptional activity leading to restoration of a more differentiated luminal CD44-/CD24+/PROCR- phenotype with low ALDH1 activity and impairment of tumor stemness." (PMID 29207686, 2017).
tumor (continued). "After demonstrating that high CD44/CD24 ratio correlated with proliferation and tumorogenesis while ALDH1+ correlated with tumor metastasis, we further verified the roles of high CD44/CD24 ratio and ALDH1+ by suppressing their expression in MDA-MB-231 cells using siRNA." (PMID 29062075, 2017). "We also evaluated the expression of pEGFR1, pγH2AX, CD24 and ALDH1 in SCC1 tumor xenografts." (PMID 28423495, 2017). "In contrast to in vitro data, we observed a significant inhibition of tumor growth in vivo in MDA-MB-231 cells (95-98% CD44+/CD24−/low; relatively high level of OCT3/4) in contrast to MCF-7 or T-47D cells (1-10% CD44+/CD24−/low; relatively low level of OCT3/4) upon TRIM28 knockdown." (PMID 27845900, 2017). "Importantly, the gene expression signatures of claudin-low tumors show a significant similarity to the signature of CD44hi/CD24-/lo mammosphere-forming cells, suggesting an enrichment in cancer stem cell (CSC)-like or tumor-initiating cell features." (PMID 28148288, 2017). "Finally, we found that the CD44/CD24 ratio and ALDH1+ were stable during the tumor growth and metastasis, from the primary tumor to the distant metastases." (PMID 29062075, 2017). "It is commonly reported that negative/low expression of CD24 is a characteristic biomarker of promoting tumor initiation and progression." (PMID 28418843, 2017). "We found that both high CD44/CD24 ratio and ALDH1+ correlated with tumor malignancy." (PMID 29062075, 2017). "PCSC co-expressing CD44/CD24/ESA showed tumor developing potential 100-fold higher than PC that do not express these molecules." (PMID 27999190, 2017). "CD24+CD44+ fraction when administered at various doses (2 × 104 down to 100 cells/mouse) did not allow the tumor growth." (PMID 28622715, 2017). "CD24 may be a downstream target of NDRG2 in cancer, and the combination of CD24 and NDRG2 is considered an effective biomarker of tumor behavior." (PMID 26506239, 2016). "An increased proportion of CD24+ and CD44+ cells in PDAC cell lines compared with the original tumor tissues might indicate that these cells had a selective advantage in cell culture." (PMID 27414409, 2016). "The data presented here also demonstrate that lack of CD24 did not significantly alter tumor initiation in any of the autochthonous tumor models studied." (PMID 26978528, 2016). "On the other hand, the expression of CD166, CD133, CD44, A2B5, CD56, NGFR and DCX seemed to be higher in UA cells, but also not statistically significant, while the expression of CD9, Nestin, GFAP, CD24, PDGFRb, PDGFRa, MAP2, TUBIII, S100 were consistently high in both UA and tumor core samples and." (PMID 27605047, 2016). "Tumor burden was independent of CD24 expression in MMTV-PyMT and TRAMP mice, and was reduced in CD24-deficient Apc1572T/+ tumors in a statistically significant manner, albeit only marginally." (PMID 26978528, 2016). "Interestingly, the two tumor initiating populations (ALDH+ cells and ESA+CD44+CD24− cells) only showed limited overlapping." (PMID 26349457, 2016). "Hence, we compared tumor growth rate following inoculation of CD24- control and CD24- IGF1R-KD cells and following inoculation of CD24+ control and CD24+ IGF1R-KD cells into the mammary fat pad of WT and MKR female mice." (PMID 27179633, 2016). "However, in PDAC there is over-expression of CD90 mainly in the stroma which is connected with tumor growth in all stages and CD90 is expressed together with CD24 but on different cells." (PMID 27332878, 2016). "NDRG2 may be a tumor biomarker, and the combination of NDRG2 with other molecules, such as CD24 and HOXD1, may yield more specific or sensitive biomarkers." (PMID 26506239, 2016). "The studies we present here suggest that although CD24 is expressed during murine mammary and prostate tumorigenesis, its genetic ablation does not affect tumor formation and growth in either model." (PMID 26978528, 2016).
tumor (continued). "Ectopic expression of Her2 allowed for culture of the HMLE cells in standard serum containing media (not shown), reduced expression of CD24, facilitated aberrant growth under 3D culture conditions and led to tumor formation in mice." (PMID 27825137, 2016). "An important finding in this study is that lack of CD24 does not significantly affect tumor incidence in any of the models investigated." (PMID 26978528, 2016). "Cells that migrated out of the tumor spheres gradually lost the expression of CD44 and CD24." (PMID 27521216, 2016). "CD133, CD44, CD24, CDCP1, CXCR4, and CD26 have been identified as colon CSC surface antigens, but it is not well defined which are the best markers to identify a tumor stem cell due to the variability found among individuals with the same tumor type." (PMID 25685060, 2015). "Pancreatic cancer stem cells (PCSC) were identified in 2007, when several groups demonstrated the presence of CD24, CD44, epithelial specific antigen (ESA) triple positive markers or CD133 positive cells had the ability to initiate tumor formation in animals at very low numbers." (PMID 26597727, 2015). "CD44 expression, a potential CSC marker, as determined in human BC CSC (phenotype CD44+/CD24-/low), was detected in scattered cells (score 1) in the 31% of the cases, or in limited tumor regions (score 2) in 15%, while 54% of tumors were negative." (PMID 25884842, 2015). "We further analyzed the excised tumor for series of CSC markers (CD44, CD24 and ABCG2)." (PMID 26176230, 2015). "In RCC, tumorigenic multipotent/bipotent CSC-like CD105+ cells lack expression of CD133 and CD24 markers, while they are present in normal adult and embryonic renal epithelial as well as in corresponding non-tumorigenic tumor-derived CD105− progenitor cells." (PMID 26210994, 2015). "We found a trend towards shorter DFS and DMFS for patients with CD24-high tumours, and CD24 is a negative prognostic factor for DFS and DMFS in this subgroup." (PMID 26444008, 2015). "A simple blood test measuring CD24 expression in PBLs can reliably differentiate between individuals with and without CR neoplasia." (PMID 26078485, 2015). "Although EpCAM, CD133, CD24 and CD44 were expressed in all three subpopulations of Li-7 cells in vitro, interestingly, they were expressed only in a very low proportion of tumor cells expressing CD13 in vivo." (PMID 25885470, 2015). "Also, membranous CD24 (SWA11) positivity (p = 0.007) and histological tumour type (p < 0.001) showed a correlation with poorer survival rates." (PMID 26578846, 2015). "To overcome the effects of heterogeneous ELF5 induction, we performed intraductal allografts of Fluorescence-Activated Cell Sorting (FACS)-sorted (Lin- and CD24+) tumor cells that were either EGFP (ELF5) positive or negative." (PMID 26717410, 2015). "Patients with early and advanced CR neoplasia express high levels of CD24 compared to individuals without such abnormalities." (PMID 26078485, 2015). "It is important to note that CD24+ cells were not able to differentiate in vitro even when co-cultured with tumor-derived fibroblasts (data not shown)." (PMID 26040280, 2015). "Following tumor cell disassociation, tumor cell samples were incubated with anti-CD44, anti-CD24, and anti-lineage mixture antibodies (PE-conjugated anti-CD2, CD3, CD10, CD16, CD18, CD31, and CD 140b), and then labeled by Aldefluor assay, and analyzed using MoFlo Astrios flow cytometry." (PMID 26932376, 2014). "All injections invariably led to tumor growth and there were no obvious differences between the CD24+ and CD24- cell subpopulations." (PMID 25216750, 2014). "The combined OR revealed CD24 expression was not related to tumor differentiation (OR = 0.81, 95% CI = 0.43–1.53, P = 0.52)." (PMID 25503963, 2014).
tumor (continued). "Immunohistochemical staining for CD24 and CD44 on tumor tissues isolated from tumor xenografts at the end of the study were performed to determine whether CD24+/CD44+ CSC maintained their phenotype at the end of the experiment." (PMID 24612587, 2014). "In contrast, tumor initiating cells from head-and-neck and breast cancer have been shown to be CD24 negative." (PMID 24760019, 2014). "Sorted CD44+CD24+ cells failed to establish large tumors within 3-4 weeks after challenge, whereas animals succumbed to the tumor within 4 weeks after challenge with sorted CD44+CD24- cells." (PMID 24324806, 2013). "In tissue sections, some tumor cells were CD44+ and others were CD24+." (PMID 24167614, 2013). "We also observed that some tumor cells were both CD44+ and CD24+." (PMID 24167614, 2013). "There is evidence that tumor cells which express CD44 and CD24, exhibit a stem-cell-like behavior." (PMID 23419168, 2013). "The removal of IFN-γ from the culture restored proliferation of tumor cells as well as the expression of neu and CD24 within 2 weeks (data not shown)." (PMID 24324806, 2013). "Tumor cells that express CD44 and CD24 exhibit a stem-cell-like behavior." (PMID 23419168, 2013). "The prevalence of a CD44+/CD24-/low tumor cell did not correlate with the event-free and overall survival and did not affect the tumor response to different treatment modalities." (PMID 23799994, 2013). "To further study the PlGF-producing cell types in the tumor parenchyma, we combined magnetic beads and FACS to isolate the three major cell populations in Tg-neu tumors, CD24+ tumor cells (luminal origin), CD31+ (endothelial cells) and CD45+ (hematopoietic cells)." (PMID 24317954, 2013). "In agreement with the CSC definition, CD44+CD24+ESA+ cells were able to give rise to a heterogeneous tumor cell population, with the expression patterns of CD44, CD24, and ESA resembling that of the primary tumor." (PMID 24213498, 2012). "Thus, both MCF-7 and R2d cells depend on estrogenic stimulation to form tumor, and respond to BBP with increased CD44 and decreased CD24." (PMID 22905168, 2012). "In this study CD44, CD24, ABCG2, and EpCAM could be detected by flow cytometry in all the RB patient tumor samples." (PMID 22328825, 2012). "Cells obtained from the xenograft tumor tissues expressed ABCG2, CD243 (p-gp) and CD24." (PMID 22844424, 2012). "In addition, the majority of the CD44/Sca1+ lung cells also expressed the surface markers CD24, ESA, or estrogen receptor (ER) at levels comparable with those expressed by primary tumor cells." (PMID 22277639, 2012). "Knock-down of CD44 or CD24 may enhance CSC differentiation to mature cells and reduce tumour progression." (PMID 22693526, 2012). "In addition, we found that Lyn and CD24 were expressed in different tumor stages of CRC and the expression level of CD24 and Lyn was positively correlated with tumor grade, tumor stage, invasion depth, and lymph node and distant metastasis." (PMID 22731636, 2012). "It should be noted that CSC were able to undergo asymmetric division also in vivo because after injection in mice, they both produced differentiated cells that constituted the bulk of the tumor and self-renewed themselves as demonstrated by the presence of CD44+CD24− cells in all excised tumors." (PMID 22328933, 2012). "As the presence of CSC in PCa and prostate cancer cell lines was recently demonstrated on the basis of the surface antigenic profile CD44+/α2β1hi/CD133+ and CD44+CD24−, respectively, in the present study we aimed to evaluate the contribution of CSC to tumor progression." (PMID 22328933, 2012). "Additionally, the up-regulation of CD5, CD24, CD70, CD226 and PDCD1 (PD-1) that usually express on the surface of T cells, B cells, dendritic cells, NK cells, and tumor cells have also been observed." (PMID 23191987, 2012).